BICD1 (BICD cargo adaptor 1)
Description:
Regulates coat complex coatomer protein I (COPI)-independent Golgi-endoplasmic reticulum transport by recruiting the dynein-dynactin motor complex.
Synonyms: Bic-D 1; BICD
Tractability: PROTAC: ubiquitination databases record sites on it; its protein half-life has been measured.
Gene: Protein-coding gene on chromosome 12 (32,106,817 to 32,383,633, forward strand). Ensembl gene ENSG00000151746.
Subcellular location: Golgi apparatus
Subcellular location (Human Protein Atlas): Vesicles
Pathways (Reactome):
Vesicle-mediated transport: COPI-independent Golgi-to-ER retrograde traffic
Gene Ontology:
Molecular function: cytoskeletal anchor activity; dynactin binding; dynein complex binding; dynein intermediate chain binding; protein binding; protein kinase binding; small GTPase binding; proteinase activated receptor binding; structural constituent of cytoskeleton
Biological process: minus-end-directed organelle transport along microtubule; positive regulation of protein localization to centrosome; positive regulation of receptor-mediated endocytosis; regulation of microtubule cytoskeleton organization; virion assembly; anatomical structure morphogenesis; constitutive secretory pathway; intracellular mRNA localization; microtubule anchoring at microtubule organizing center; negative regulation of phospholipase C-activating G protein-coupled receptor signaling pathway; RNA processing; stress granule assembly
Cellular component: centrosome; cytoplasmic microtubule; cytoplasmic vesicle; cytosol; Golgi apparatus; membrane; perinuclear region of cytoplasm; secretory vesicle; trans-Golgi network; cytoskeleton
Genetic constraint (gnomAD): Loss-of-function variants: 35 observed, 95.25 expected, observed/expected ratio (o/e) 0.37, 90% interval 0.28 to 0.49. The upper end of that interval is the gene's LOEUF score, 0.49, which puts it in group 2 of 6, group 1 being the genes least tolerant of losing a copy. Missense variants: 950 observed, 1,243.2 expected, observed/expected ratio (o/e) 0.76, 90% interval 0.72 to 0.81. Synonymous variants: 429 observed, 491.67 expected, observed/expected ratio (o/e) 0.87, 90% interval 0.81 to 0.94.
Homologues: Orthologues: chimpanzee BICD1 (99% identical), macaque BICD1 (99% identical), pig BICD1 (99% identical), dog BICD1 (98% identical), rat Bicd1 (96% identical), mouse Bicd1 (96% identical), guinea pig BICD1 (94% identical), rabbit BICD1 (92% identical), tropical clawed frog bicd1 (77% identical), zebrafish bicd1a (60% identical), Drosophila melanogaster BicD (33% identical), Caenorhabditis elegans bicd-1 (24% identical). Paralogues in human: BICD2 (54% identical).
Diseases named in the same sentence as BICD1 in open-access papers:
BICD1 is named in the same sentence as 28 diseases in open-access papers, as found by Europe PMC text mining. Sharing a sentence is not in itself a finding about the gene and the disease. The quoted sentences say what the papers report.
emphysema (3 papers, 2012 to 2022). "Recently, genome-wide association study identified bicaudal D homolog 1 (BICD1) as a susceptibility gene for emphysema." (PMID 22251849, 2012). "Additionally, susceptibility to emphysema has been recently linked to a variant (single nucleotide polymorphisms; SNP) of the BICD1 gene." (PMID 35330379, 2022). "Previously reported associations of these genetic variants include: airflow limitation (CHRNA3/5, IREB2, HHIP), emphysema susceptibility and severity (CHRNA3/5, BICD1), chronic bronchitis phenotype, exacerbation rate (HHIP) and pulmonary hypertension pathogenesis." (PMID 35330379, 2022). "Kong et al19 recently identified in a genome‐wide association study of emphysema an association of a single‐nucleotide polymorphism in bicaudal‐D1 (BICD1) with the presence or absence of emphysema." (PMID 32123815, 2019).
glioblastoma (3 papers, 2017 to 2021). The most malignant astrocytic tumor (WHO grade IV). "Bicd1 (BICD cargo adaptor 1) is a hub gene in this module, and its expression is strongly correlated with EMT and worse prognosis in glioblastoma." (PMID 32831131, 2020). "A recent study demonstrated that upregulation of the BICD1 gene is a predictor for poor prognosis and poor response to Temozolomide (TMZ) in glioblastoma (GBM) patients." (PMID 34439934, 2021).
glioma (3 papers, 2017 to 2022). A benign or malignant brain and spinal cord tumor that arises from glial cells (astrocytes, oligodendrocytes, ependymal cells). "High BICD1 expression also showed more significant impact (P=0.009932) than high MGMT expression (P=0.028420) on worse overall survival in the CGGA (Chinese Glioma Genome Atlas) cohort." (PMID 29371945, 2017). "The percentage of high BICD1 expression was significantly correlated with poor prognosis in glioma patients when they are grouped according to the WHO grade and patient age in the TCGA GBMLGG cohort (P<0.00001)." (PMID 29371945, 2017). "The heatmap revealed that downregulation of the BICD1 gene was more enriched in grade II gliomas than in grade III gliomas, and the t-test analysis revealed that the expression levels of BICD1 were significantly lower in grade II gliomas than in grade III gliomas." (PMID 34439934, 2021). "In comparison of BICD1 with MGMT expression in predicting the overall survival of glioma patients by the Kaplan-Meier survival analysis, high BICD1 expression showed more significant impact (P<0.000001) than high MGMT expression (P=0.00003) on worse overall survival in the TCGA GBMLGG cohort." (PMID 29371945, 2017). "GBMs (grade IV gliomas) had apparently higher BICD1 expression than LGGs (grades II and III gliomas) in the TCGA GBMLGG cohort (n=689)." (PMID 29371945, 2017). "First, high BICD1 expression was correlated with poor prognosis in the TCGA GBM cohort (n=523) and in the CGGA glioma cohort (n=220)." (PMID 29371945, 2017). "In this study, we identified BICD1 expression as a potential biomarker from cell-based microarray data, and validated its prognostic value in clinical datasets of the TCGA GBM and GBMLGG cohorts, and the CCGA glioma cohort." (PMID 29371945, 2017).
hepatocellular carcinoma (2 papers, 2021 to 2022). A malignant tumor that arises from hepatocytes. "GTF2H5, BICD1, and CLK3 have been reported to be oncogenes in ovarian cancer and hepatocellular carcinoma and are strongly associated with prognosis." (PMID 36212157, 2022). "Another study also reported that BICD1 functions as a prognostic biomarker and promotes hepatocellular carcinoma (HCC) progression." (PMID 34439934, 2021). "ALDH2 is an important tumor suppression gene in the pathogenesis of hepatocellular carcinoma, which may give us a hint that the favorable outcome of LGG patients with BICD1 downregulation is probably due to upregulation of the tumor suppression gene, ALDH2." (PMID 34439934, 2021).
astrocytomas (1 paper, 2021). "Although BICD1 expression in oligodendrogliomas was detected to be slightly higher than that of astrocytomas, the difference was not statistically significant (p = 0.6061)." (PMID 34439934, 2021). "However, in the histological subtypes of LGGs, including oligodendroglioma and astrocytoma, BICD1 was not differentially expressed." (PMID 34439934, 2021).
chronic obstructive pulmonary disease (1 paper, 2019). A chronic and progressive lung disorder characterized by the loss of elasticity of the bronchial tree and the air sacs, destruction of the air sacs wall, thickening of the bronchial wall, and mucous accumulation in the bronchial tree. "Bicaudal D1 (BICD1), an adaptor for the dynein‐dynactin motor complex, has been identified as a susceptibility gene in chronic obstructive pulmonary disease (COPD)." (PMID 32123815, 2019).
colon cancer (1 paper, 2022). "Our findings indicated that DEDD2, GTF2H5, SNRPA1, BICD1, CELF1, and CLK3 were prognostic risk factors for colon cancer, while ADAD1, CMTR1, HNRNPUL1, FTSJ3, WDR43, THUMPD3, SNRPF were prognostic protective factors." (PMID 36212157, 2022). "We then performed immunohistochemistry to compare the expression levels of BICD1 in normal and cancer tissues in colon cancer patients, but the results showed that BICD1 expressed negatively in both tissues." (PMID 36212157, 2022). "As alterations in mRNA stability and/or translational efficiency are increasingly reported in colorectal cancer, we hypothesize that post-transcriptional alterations of BICD1 may be present in colon cancer tissues and are conducting related experiments." (PMID 36212157, 2022).
hearing loss (1 paper, 2023). "Our findings indicate that bi-allelic loss-of-function variants in BICD1 are associated with hearing loss and peripheral neuropathy." (PMID 37240244, 2023). "The screening of BICD1 should be considered for individuals with co-occurring hearing loss and peripheral neuropathy and in individuals with isolated hearing loss or peripheral neuropathy." (PMID 37240244, 2023). "In this study, we provide genetic evidence that bi-allelic loss-of-function variants in the BICD1 gene may cause peripheral neuropathy and hearing loss." (PMID 37240244, 2023).
neuroblastoma (1 paper, 2019). Neuroblastoma (NB) is the most common solid, extracranial childhood tumor. "We investigated the effect BICD1 or BICD2 silencing on HIF1α nuclear translocation in SK-N-MC neuroblastoma cell line as a non-MSC cell model." (PMID 30464225, 2019).
pancreatic cancer (1 paper, 2022). "BICD1 encode a protein Bicaudal-D homolog 1 and has been reported with association of telomere length variation, which is implemented in pancreatic cancer cells." (PMID 35939448, 2022). "In addition, a genome-wide association study (GWAS) reported that a SNP located at the second intron of BICD1 is significantly associated with susceptibility to pancreatic cancer." (PMID 35939448, 2022).
prostate tumors (1 paper, 2019). "In addition, seven other genes, GGT1, HDAC1, KLK2, MYO6, PLA2G7, BICD1, and CACNAID, were found to be differentially expressed in prostate tumors of non-BCR and BCR patients." (PMID 31741711, 2019).
cancer (4 papers, 2017 to 2022). A tumor composed of atypical neoplastic, often pleomorphic cells that invade other tissues. "Our findings confirmed that downregulation of BICD1 is a favorable prognostic marker and is highly correlated with downregulation of several important markers associated with cancer progression, including CD274 (PD-L1), in LGGs in the CGGA and CCLE datasets." (PMID 34439934, 2021). "Our findings may possibly explain why downregulation of BICD1 contributed to a favorable outcome in LGG patients by connecting it with the suppression of pathways associated with cancer progression." (PMID 34439934, 2021). "To explore other possible mechanisms, we attempted to analyze the correlation of BICD1 downregulation with a couple of markers involved in various pathways associated with cancer progression, including the immune checkpoint, MET, STAT, and MTOR pathways, in the TCGA LGG cohort." (PMID 34439934, 2021). "In our result, we also found BICD1 expression was significantly correlated with IDH1 expression, instead of the IDH1 mutant status, which suggested an emerging role of BICD1 in IDH1-mediated cancer metabolism." (PMID 29371945, 2017). "This may suggest a possible connection between BICD1 expression and EMT processing, which was associated with therapeutic resistance in cancers." (PMID 29371945, 2017). "In these cancers, several biomarkers have been described as predicting therapeutic outcomes, e.g., CDCA7L, BICD1, DDX17, S1PR1 and SEPT7." (PMID 33260776, 2020).
tumor (3 papers, 2017 to 2025). "Patients with high BICD1 expression spent a significantly shorter time to experience a new tumor event, tumor progress, and tumor recurrence than those with low BICD1 expression." (PMID 29371945, 2017). "And the time to experience tumor recurrence was significantly shorter in patients with high BICD1 expression (P=0.000117) than in those with high MGMT expression (P=0.005083)." (PMID 29371945, 2017). "The time to experience a new tumor event was significantly shorter in patients with high BICD1 expression (P=0.000127) than in those with high MGMT expression (P=0.008955)." (PMID 29371945, 2017). "The time to experience tumor progression was also significantly shorter in patients with high BICD1 expression (P=0.000321), while it was not significantly shorter in patients with high MGMT expression (P=0.469433)." (PMID 29371945, 2017).
infection (1 paper, 2025). The state of being infected such as from the introduction of a foreign agent such as serum, vaccine, antigenic substance or organism. "We next determined whether BICD1/2 adaptors are used by O. tsutsugamushi during infection." (PMID 40610402, 2025). "We show that ScaC is sufficient to engage dynein-based motility in the absence of other bacterial proteins and that BICD1 and BICD2 are required for efficient movement of O. tsutsugamushi during infection." (PMID 40610402, 2025).
neurological disease (1 paper, 2023). "Here, we implicate another BICD family member, BICD1, which has previously been linked to the modulation of the endosomal sorting of activated neurotrophin receptors in neurons in a human neurological disease." (PMID 37240244, 2023).
peripheral neuropathy (1 paper, 2023). A disorder affecting the peripheral nervous system. "Definitive evidence that bi-allelic loss-of-function variants in BICD1 cause peripheral neuropathy and hearing loss will require the identification of other families and individuals with similar variants with the same phenotype." (PMID 37240244, 2023). "Using exome sequencing, we identified a novel homozygous frameshift variant in the BICD1 gene, which co-segregated with hearing loss and peripheral neuropathy in a large family of Ashkenazi Jewish descent." (PMID 37240244, 2023). "A homozygous frameshift variant in the BICD1 gene, c.1683dup (p.(Arg562Thrfs*18)), was identified in the proband and segregated with hearing loss and peripheral neuropathy in the family." (PMID 37240244, 2023). "It is possible that other variants in BICD1 may cause isolated hearing loss or isolated peripheral neuropathy." (PMID 37240244, 2023).
BICD1 also shares sentences with these, for which no sentence is quoted: cyst (2 papers); Autoimmunity (1); bacterial infection (1); CNS tumors (1); colorectal cancer (1); oligodendroglioma (1); ovarian carcinoma (1); Parkinsonism (1); prostate carcinoma (1); psychiatric disorder (1); Wilson disease (1); –muscular atrophies (1).